NPY2R (neuropeptide Y receptor Y2)
Description:
Receptor for neuropeptide Y (NPY) and peptide YY (PYY). Can also bind with lower affinity pancreatic polypeptide (PP/PPY) and [Leu-31, Pro-34]NPY, an analog of NPY modified at residues 31 and 34 of the mature form. NPY or PYY binding induces adenylate cyclase-inhibiting G protein-coupled receptor signaling, resulting in inhibition of cAMP production. Receptor activation by ligands also leads to an increase of intracellular Ca(2+) levels. Involved in the regulation of colonic antisecretory tone, and colonic contractility (By similarity). As receptor for peptide PYY(3-36) in the arcuate nucleus of the hypothalamus, it is involved in the down-regulation of appetite and food intake (By similarity).
Synonyms: NPY2-R
Tractability: Small molecule: a high-quality ligand is known; it belongs to a druggable protein family. Antibody: its Gene Ontology location is reachable by antibodies, with high confidence; UniProt places it where antibodies can reach, with medium confidence; UniProt predicts a signal peptide or a membrane-spanning region. PROTAC: a small molecule that binds it is known. Other modalities: a drug acting on it is in phase 2 or 3 trials.
Target class: Neuropeptide Y receptor; Peptide receptor (family A GPCR); Membrane receptor; Family A G protein-coupled receptor; Short peptide receptor (family A GPCR)
Chemical probes: BIIE0246 (high quality), CHEMBL2307889, CHEMBL2440185, ML072, ML073, ML074, ML075 (high quality), NPY-(13-36) (pig)
Gene: Protein-coding gene on chromosome 4 (155,208,636 to 155,217,078, forward strand). Ensembl gene ENSG00000185149.
Subcellular location: Cell membrane
Pathways (Reactome):
Signal Transduction: G alpha (i) signalling events; Peptide ligand-binding receptors
Gene Ontology:
Molecular function: G-protein alpha-subunit binding; neuropeptide receptor activity; neuropeptide Y receptor activity; peptide YY receptor activity; protein binding; calcium channel regulator activity; signaling receptor activity; G protein-coupled receptor activity
Biological process: adenylate cyclase-inhibiting G protein-coupled receptor signaling pathway; cardiac left ventricle morphogenesis; G protein-coupled receptor signaling pathway; outflow tract morphogenesis; locomotory behavior; negative regulation of eating behavior; neuropeptide signaling pathway; regulation of peptide secretion; negative regulation of neuronal action potential; negative regulation of peptide secretion
Cellular component: cilium; plasma membrane; 9+0 non-motile cilium; membrane; non-motile cilium
Genetic constraint (gnomAD): Loss-of-function variants: 17 observed, 23.63 expected, observed/expected ratio (o/e) 0.72, 90% interval 0.49 to 1.08. The upper end of that interval is the gene's LOEUF score, 1.08, which puts it in group 4 of 6, group 1 being the genes least tolerant of losing a copy. Missense variants: 424 observed, 491.73 expected, observed/expected ratio (o/e) 0.86, 90% interval 0.8 to 0.93. Synonymous variants: 209 observed, 193.92 expected, observed/expected ratio (o/e) 1.08, 90% interval 0.96 to 1.21.
Homologues: Orthologues: chimpanzee NPY2R (100% identical), macaque NPY2R (99% identical), rabbit NPY2R (96% identical), pig NPY2R (95% identical), mouse Npy2r (94% identical), rat Npy2r (94% identical), guinea pig NPY2R (93% identical), tropical clawed frog npy2r (70% identical), dog NPY2R (66% identical), zebrafish npy2rl (59% identical), zebrafish npy2r (55% identical). Paralogues in human: GPR83 (31% identical), PRLHR (31% identical), NPY4R (27% identical), NPY4R2 (27% identical), NPY1R (26% identical), NPY5R (25% identical), TACR2 (25% identical), TACR3 (25% identical), TACR1 (25% identical), PROKR2 (23% identical), PROKR1 (23% identical), GPR19 (22% identical), and 21 more.
Diseases named in the same sentence as NPY2R in open-access papers:
NPY2R is named in the same sentence as 55 diseases in open-access papers, as found by Europe PMC text mining. Sharing a sentence is not in itself a finding about the gene and the disease. The quoted sentences say what the papers report.
Obesity (18 papers, 2015 to 2026). Accumulation of substantial excess body fat. "When co-activated with GLP-1R, NPY2R induces greater weight loss, improves insulin sensitivity and restores beta cell function in mouse models of obesity/type 2 diabetes." (PMID 41094027, 2026). "NPY2R’s rs6857715 variant associates not only with more severe obesity, but also with atypical depression." (PMID 41375608, 2025). "Other NPY2R variants, such as rs12649641, rs2342676, and rs6857530, have additive effects with other significant obesity–depression genes (e.g., FTO and MC4R)." (PMID 41375608, 2025). "NPY2R polymorphisms have been associated with BMI and show gender-specific effects; for instance, certain SNVs in this gene appear to influence obesity risk exclusively in men." (PMID 39858569, 2024). "Similarly, variants of the neuropeptide Y receptor, NPY2R, have been linked to comorbid depression and obesity." (PMID 41375608, 2025). "NPY2R, in turn, encodes a that inhibits appetite regulation, thereby contributing to obesity." (PMID 41153348, 2025). "Notably, variants in the CDKAL1, ADCY3, ADRA2A, and NPY2R genes showed strong associations with metabolic traits such as waist circumference, insulin resistance, and obesity." (PMID 39858569, 2024). "Interestingly, related genetic variants in PYY (encoding the ligand for NPY2R) have been associated with obesity-related traits solely in women." (PMID 39858569, 2024). "Glucocorticoid increased NPY2R in adipocytes of the abdominal fat and induced angiogenesis and adipogenesis, resulting in obesity and metabolic syndrome." (PMID 37653540, 2023). "The human neuropeptide Y receptor Y2 (Y2R) is a drug target for the treatment of obesity and anxiety." (PMID 33531491, 2021). "NPY2R was first described in 1996; it is an appetite hormone and candidate gene for obesity development and control of food intake." (PMID 29312906, 2017). "This study using mice provides strong evidence that up-regulation of NPY secretion and NPY2R expression within visceral fat contributes to obesity and metabolic syndrome in mammals." (PMID 26445145, 2015). "Also among these genes is the neuropeptide Y receptor type 2 (Npy2r) which is a receptor for both NPY and peptide YY, variants of which are associated with obesity." (PMID 33424545, 2020). "Moreover, NPY raises the risk of obesity by upregulating NPY and NPY2R expression in the abdominal fat and its administration in rodents leads to lipogenic enzyme activation in adipose tissues, demonstrating its critical role in adipogenesis." (PMID 30105036, 2018). "This study demonstrates experimentally that pre-stroke pharmacological targeting of obesity by GLP-1R and NPY2R activation in type 2 diabetes enhances stroke recovery, without effects additional to weight loss mediated by the treatments." (PMID 41094027, 2026). "Obesity and adiposity are influenced by genes like ADCY3, NPY2R, and SEC16B, which play central roles in MetS pathophysiology." (PMID 39858569, 2024). "Specifically, the mislocalization of some receptors, such as neuropeptide Y receptor Y2 (NPY2R), serotonin 5-hydroxytryptamine (HT)2C receptor (5-HT2CR), and leptin receptor, in the hypothalamus may lead to hyperphagia and obesity." (PMID 37466224, 2023). "Moreover, despite the anti-obesity role of NPY2R at the hypothalamic level, in WAT, NPY2R stimulates adipogenesis and angiogenesis, a process crucial to healthy WAT expansion." (PMID 36830982, 2023). "Since the GLP-1R and NPY2R differ with respect to their tissue distribution and signaling properties, a dual agonist peptide such as EP45 might constitute an ideal medicinal agent with which to simultaneously treat T2DM and obesity." (PMID 29491394, 2018). "Within the ARC, we also did not observe changes in NPY2R cilia between sexes, in HFD-induced obesity or at different circadian times." (PMID 36849261, 2023).
Obesity (continued). "Indeed, as stress exaggerates diet-induced obesity through neuropeptide Y (NPY)-mediated pathway in visceral WAT38, we observed higher gene expression of NPY receptor (Npy2r) in PWAT of Ob-IF mice, compared to Ob-PF mice (data not shown)." (PMID 30792482, 2019).
Anxiety (10 papers, 2017 to 2026). Intense feelings of nervousness, tension, or panic often arise in response to interpersonal stresses. "This is complemented by data indicating that neuropeptide Y receptor Y2 (npy2r) deficiency reduces anxiety and increases food intake." (PMID 39275174, 2024). "The increased mRNA expression of NPY receptors, especially NPY2R, has been observed in depression subjects which is suggestive of aggravated anxiety; however, the results in our study were not in consonance with the previous finding." (PMID 40636521, 2025). "We detected the expression levels of anxiety-related genes (th1, th2, gr1, gr2, mr) by qRT-PCR, the results showed that the expression levels of th1, th2, gr1, gr2, and mr gene in npy2r+/− medaka decreased significantly." (PMID 38020893, 2023). "So far, this is the first npy2r gene knockout model established in fish and demonstrates that npy2r plays an important role in the regulation of reproduction, feeding and anxiety in fish." (PMID 38020893, 2023). "Through maze experiment, open field and light/dark test, it has been demonstrated that npy2r plays an important role in anxiety and stress-related behavior in mice." (PMID 38020893, 2023). "Previous studies have demonstrated that npy2r plays an important role in anxiety and stress-related behavior in mice using elevated maze, open field, and light/dark tests, and our study is consistent with previous research." (PMID 38020893, 2023). "Neuropeptide Y receptor Y2 (npy2r) is an important receptor gene involved in anxiety and feeding regulation in mammals." (PMID 38020893, 2023). "At present, the establishment of npy2r knockout mice model revealed that npy2r plays an important role in anxiety behavior, feeding activity and learning." (PMID 38020893, 2023). "ASM hyperactivity leads to an over-expression of anxiety-related genes coding for the neuropeptide Y receptor Y2 (NPY-RY2) and gamma-aminobutyric acid A receptor, subunit alpha 5 (α5-GABAA-R)." (PMID 28000031, 2017). "The role of NPY2R+ amygdala neurons in anxiety-like behaviors appears to paint a complex picture." (PMID 38826337, 2024). "Given the pivotal role of the CeA in processing itch- and pain-induced negative affect, we investigated whether optogenetic stimulation of NPY2R+ amygdala neurons affects anxiety-like behavior and explored potential lateralization effects." (PMID 38826337, 2024). "Therefore, the present study suggests that npy2r is involved in the regulation of anxiety behavior in medaka." (PMID 38020893, 2023). "The mirror test and open field test showed that npy2r+/− medaka improved sociability and reduced anxiety-like behavior, qRT-PCR analysis showed that the expression levels of anxiety related genes (th1, th2, gr1, gr2, and mr) in npy2r+/− medaka were significantly decreased." (PMID 38020893, 2023). "In previous reports, while the intra-CeA injection of an NPY2R antagonist reduced anxiety-like behavior, the intra-basolateral amygdala (-BLA) injection of an NPY2R agonist produced a similar effect." (PMID 38826337, 2024). "Optogenetic stimulation of NPY2R+ neurons in the CeA failed to elicit alterations in anxiety-like behaviors or locomotion activity." (PMID 38826337, 2024). "This suggests that NPY2R+ amygdala neurons may not substantially contribute to anxiety-like behavior." (PMID 38826337, 2024). "However, it is not clear whether npy2r has the similar function in fish as in mammals, especially the knowledge related to anxiety and feeding." (PMID 38020893, 2023).
depression (4 papers, 2019 to 2025). "Nominally significant findings were noted for HTR1A and NPY2R, where women with untreated depression displayed higher gene expression than healthy controls (p < 0.05), whereas women on antidepressant treatment had similar expression as healthy controls." (PMID 31805950, 2019). "Post hoc analyses revealed that women with untreated depression had higher gene expression of HTR1A, (p = 0.039) and NPY2R (p = 0.025) than healthy controls, whereas women on antidepressant treatment had similar expression levels of HTR1A and NPY2R as healthy controls." (PMID 31805950, 2019).
neuroblastoma (4 papers, 2015 to 2022). Neuroblastoma (NB) is the most common solid, extracranial childhood tumor. "NPY2R is often strongly expressed in neuroblastomas, paragangliomas, and renal carcinomas, and NPY2R agonists such as BIM-43004-1 suppress the growth of human pancreatic cancer xenografts in mice." (PMID 29100314, 2017).
Anorexia (2 papers, 2013 to 2021). Lack of desire to eat (loss of appetite). "Although we didn’t detect the expression of NPY receptor 2 (NPY2R), its’ possible role in the regulation of AMPH-induced anorexia should be considered." (PMID 24225225, 2013). "As demonstrated here, administrations of PYY and DON elicited anorexia, and JNJ-31020028 could attenuate anorexic response, indicating that NPY2R plays an important part in DON-induced anorexia." (PMID 34437383, 2021).
diabetes (2 papers, 2020 to 2026). "We determined experimentally that pre-stroke weight loss by GLP-1R/NPY2R activation strongly improves stroke recovery in diabetes." (PMID 41094027, 2026).
epilepsy (2 papers, 2020 to 2024). A brain disorder characterized by episodes of abnormally increased neuronal discharge resulting in transient episodes of sensory or motor neurological dysfunction, or psychic dysfunction. "The evidence chains also indicate a connection between Ibudilast and FXS through epilepsy, mediated by the neuropeptide Y receptor protein NPY2R." (PMID 38977662, 2024).
type 2 diabetes (2 papers, 2018 to 2026). "Although speculative, these findings imply that individuals with type 2 diabetes receiving GLP-1R and/or NPY2R agonists to treat their underlying diseases could possibly profit from both these effects." (PMID 41094027, 2026).
breast carcinoma (1 paper, 2025). "In breast cancer, NPY1R expression was confirmed in 85% of primary human breast carcinomas and 100% of lymph node metastases exhibiting a switch from NPY2R expression in normal breast tissue to NPY1R dominant expression during cancer progression." (PMID 40073121, 2025).
Childhood Cancer (1 paper, 2021). "One genome-wide association study (GWAS) in CCSs using data from the SJLIFE and the Childhood Cancer Survivor Study identified a haplotype formed by 4 of 13 SNPs, located upstream of the neuropeptide receptor 2 gene (NPY2R) associated with premature menopause." (PMID 34572825, 2021).
colon cancer (1 paper, 2025). "However, other NPY receptors have been implicated in promoting tumorigenicity in other cancers; for example, NPY2R is up-regulated in vascular endothelial growth factor A–depleted orthotopic models of colon cancer, and NPY2R antagonists inhibited angiogenesis and tumor growth in these models." (PMID 40073121, 2025).
endometritis (1 paper, 2023). An acute or chronic, usually bacterial infectious process affecting the endometrium. "Acute endometritis induced NPY2R in gilt myometrium, and affected uterine contractility." (PMID 37653540, 2023).
glioblastoma (1 paper, 2025). The most malignant astrocytic tumor (WHO grade IV). "The neuropeptide-related genes, including PPY and members of the NPY family (e.g., NPY, NPY1R, NPY2R, NPY4R, NPY5R, PYY), form a distinct cluster characterized by strong co-expression and shared pathway interactions, indicating a potential role in neuroendocrine signaling relevant to glioblastoma." (PMID 40725410, 2025).
Huntington disease (1 paper, 2022). Huntington disease (HD) is a rare neurodegenerative disorder of the central nervous system characterized by unwanted choreatic movements, behavioral and psychiatric disturbances and dementia. "NPY receptor gene NPY2R previously had been reported to be involved in neurodegenerative disorders such as Huntington’s disease." (PMID 35208605, 2022).
Hyperinsulinemia (1 paper, 2015). An increased concentration of insulin in the blood. "In mice, a triple knockout of NPY1R, NPY2R and NPY4R prevents the hyperinsulinemia associated with NPY overexpression, indicating that NPY signalling through the NPY receptors modulates insulin secretion." (PMID 26138755, 2015).
hypothyroidism (1 paper, 2021). Abnormally low levels of thyroid hormone. "Besides, we did not observe any changes in the NPY2R expression in patients with AIT-related hypothyroidism along with postoperative hypothyroidism." (PMID 34104248, 2021).
insulinoma (1 paper, 2015). "We show via an in vitro binding assay that miR-9a binds to sNPFR1 mRNA in insect cells and to the mammalian orthologue NPY2R in rat insulinoma cells." (PMID 26138755, 2015). "Consequently, miR-9a transfection reduces sNPFR1 and NPY2R protein levels compared with an actin control in both Drosophila S2 and rat insulinoma cells, respectively." (PMID 26138755, 2015).
itch (1 paper, 2024). "Collectively, these findings provide substantial support for the role of NPY2R+ CeA neurons in regulating itch signals." (PMID 38826337, 2024).
lymph node metastasis (1 paper, 2017). "In patients without lymph node metastasis (n = 100), methylation of NPY2R (compared with methylation of the other seven genes) best correlated with poor disease-free survival (DFS) (odds ratio, 2.492; 95% CI, 1.190–5.215; P = 0.015)." (PMID 29100314, 2017). "Notably, the odds ratio was significantly higher in patients with no lymph node metastasis (n = 100) in whom the NPY2R promoter was methylated versus unmethylated (odds ratio, 2.492; 95% CI, 1.190–5.215; P = 0.015)." (PMID 29100314, 2017).
memory impairment (1 paper, 2024). "Genes involved in neuroactive ligand–receptor interactions, such as Npy2r, Htr2c, and Rxfp1, were significantly dysregulated during cognitive dysfunction or memory impairment which was tightly related with tinnitus." (PMID 38562529, 2024).
neuropathic pain (1 paper, 2022). Chronic pain caused by damage to nerve fibers. "The expression of NPY and NPY2R was found to be aberrantly up-regulated in neuropathic pain-related microarray dataset." (PMID 35313782, 2022). "It seemed that the effect of NPY in amygdala in neuropathic pain may be associated with NPY2R, we further explored the regulatory mechanism of NPY2R on MAPK pathway in neuropathic pain." (PMID 35313782, 2022).
oral cancer (1 paper, 2017). "In patients with oral cancer (n = 69), methylated NPY1R and NPY2R were independent prognostic factors for poor DFS, both individually and, even more so, in combination (odds ratio, 3.90; 95% CI, 1.523–9.991; P = 0.005)." (PMID 29100314, 2017).
oropharyngeal cancers (1 paper, 2017). Carcinoma, predominantly squamous cell, arising from the epithelial cells of the oropharynx. "Our study associates NPY1R, NPY2R, and NPY4R methylation with tumor recurrence in oral and oropharyngeal cancers." (PMID 29100314, 2017). "Similar findings were observed for NPY2R and NPY4R in patients with oropharyngeal cancer (n = 162) (odds ratio, 5.663; 95% CI, 1.507–21.28; P = 0.010)." (PMID 29100314, 2017). "The present study suggests that the methylation status of the NPY1R, NPY2R, and NPY4R genes is an independent indicator of DFS in patients with oral and/or oropharyngeal cancers." (PMID 29100314, 2017).
Pain (1 paper, 2025). An unpleasant sensory and emotional experience associated with actual or potential tissue damage, or described in terms of such damage. "In conclusion, this study reveals the Npy2r sensory neuron‐mediated lung‐to‐brain pathway to activate vlPAG for MSC‐induced analgesic effects in the mouse model of neuropathic pain." (PMID 40874463, 2025).